ITGAV (integrin subunit alpha V)
Diseases named in the same sentence as ITGAV in open-access papers (continued):
Sharing a sentence is not in itself a finding about the gene and the disease.
cancer (continued). "Indeed, ITGAV contributes to IGF1R-mediated EMP in epithelial plastic cancer cells." (PMID 39075581, 2024). "Interestingly, Rel-PT had a higher percentage of ITGAV+ cancer cells without Vim expression than NR-PT, suggesting that ITGAV also identifies an emerging epithelial plastic cancer cell population in Rel-PT samples that cannot yet be identified by mesenchymal markers in regular IF assays." (PMID 39075581, 2024). "Moreover, MDA‐MB‐231 cells grown in FN‐silk networks had high cancer stem cell markers (i.e., NANOG, OCT4, and SOX2), accompanied by an up‐regulation of genes associated with basement membrane degradation and invasiveness (i.e., HIF1α, ITGAV, and MMP14)." (PMID 37693069, 2023). "Thus, it is necessary to comprehensively explore ITGAV expression in many cancers." (PMID 35927660, 2022). "Thus, a positive correlation between ITGAV expression and macrophage infiltration levels may support its relationship with poor prognosis in cancer patients." (PMID 35927660, 2022). "Here, we propose a novel mechanism in cancer, wherein elevated MEK/ERK signaling leads to GCIP down-regulation and thereby enhances ITGAV expression and cell migration." (PMID 39955062, 2025). "To explore the relationship between ITGAV expression and DFS across various cancer types, we performed Cox regression analysis." (PMID 40775249, 2025). "Functional inference also indicated enrichment of cancer-related orthologs such as LKB1, NFKB1, ITGAV, and TRAF4." (PMID 41356699, 2025). "Subsequent survival analysis revealed that, except for KIRC, cancers with high ITGAV expression were associated with lower DSS than those with low expression, suggesting that higher ITGAV levels may be indicative of worse disease-specific survival in most cancer types." (PMID 40775249, 2025). "Among of them, SLC12A5, MYO1B, FBN1, ITGAV, KLF4 and USP28 were more reported to effect cell proliferation and migration in human cancers." (PMID 39951205, 2025). "Our results identified ITGAV (integrin αV) and its heterodimer partner ITGB5 (integrin β5) as the essential integrin α/β pair for cancer cell expansion." (PMID 38316881, 2024). "We did observe more protein complexes appearing in the migratory cancer cells, and THBS1 functions as an important mediator with TβRI and ITGAV." (PMID 39304722, 2024). "Using the PanCan Atlas from TCGA, expression of ITGAV and COL4A1 transcripts was found to be the highest in ccRCC specifically, compared to all other cancers." (PMID 39639369, 2024). "These validation screens suggested that in addition to those targeting ITGAV, the sgRNAs targeting ITGB5 were strongly depleted in both cancer cell models." (PMID 38316881, 2024). "The list was narrowed down to the two candidate genes, which shared the maximum overlap between the cancer types, including NPC2 and ITGAV." (PMID 39690926, 2024). "TGFβ1 also induced ITGAV expression in sh-control plastic cancer cells, while this effect was significantly reduced in sh-IGF1R cancer cells." (PMID 39075581, 2024). "Protein docking analysis showed that 23 interface residues of ANGPTL3 interact with 23 residues of cancer-suppressing ITGB3 and ITGAV proteins." (PMID 37375208, 2023). "Further CellChat analysis revealed that the signaling pathways between cancer cells and identified CAFs (NRG1-ERBB2/4 and FN1-CD44/ITGAV/ITGA3/ITGB6/ITGB8/ITGB1) were specifically enriched in CAde and CSCC, respectively." (PMID 37879219, 2023). "Summary of top four selected genes (COL5A2, ITGAV, SPARC and ACTA2) which were correlated with EMT signature in 32 pan cancer cohorts was presented in radar graphs, and the well-known CDH1 (Epithelial) and VIM (Mesenchymal) genes were included as controls." (PMID 35046456, 2022). "Positive associations (Pearson correlation coefficient > 0.2, p < 0.05) of ITGAV expression with resting CD4 memory T cells, M1 macrophages, and M2 macrophages were observed in at least ten cancers." (PMID 35927660, 2022).
cancer (continued). "Little is known about the relationship between integrin subunit alpha V (ITGAV) and cancers, including small cell lung cancer (SCLC)." (PMID 35927660, 2022). "By contrast, the FN1-related molecular pairs, including FN1-CD44 (a marker of cancer stem cells) and FN1-(ITGAV + ITGB1), were prompted between SELENOP-Mφ/SPP1-Mφ and FABP4-Mφ/FCN1-Mφ/CD4/CD8 cells in LUAD." (PMID 36008393, 2022). "The upregulation of ITGAV and ITGB3 can make the cancer cells resistant to chemotherapy by different groups." (PMID 34680783, 2021). "Lower plasma levels were found for ITGAV and CEACAM1 in patients with cancer compared to patients with benign tumors." (PMID 33075095, 2020). "A six-biomarker model (HE4, CA125, CXCL1, ITGAV, CEACAM1, IL-10RB and age) was the best model for discrimination between benign tumors and borderline tumors + cancer, with AUC 0.868 and sensitivity 0.86 / specificity 0.82 at best point cut-off (p = 0.016)." (PMID 33075095, 2020). "Most of the proteins were up-regulated in cancer patients although lower NPX levels were seen for two proteins, ITGAV and DNER, in cancer patients." (PMID 33075095, 2020). "Cancer patients with high CCN1 expression have poor survival outcomes and positive correlation with ITGAV and ITGB3 and high YAP/WWTR1." (PMID 31429823, 2019). "Importantly, RNA-seq indicated DNAJC10 downregulates CAMs-related genes such as ITGAV, SEMA3C, DPP4, and ITGA1, which promote cancer cell migration and invasion." (PMID 41191192, 2025). "Furthermore, Heatmap analysis showed DNAJC10 overexpression reduced transcription of CAMs related genes such as ITGAV, SEMA3C, DPP4, and ITGA1, which are reported to enhance cancer cell migration and invasion." (PMID 41191192, 2025). "Although we detected some ITGAV+ cancer cells without Vim expression in both conditions, ITGAV expression was closely associated with Vim expression, as previously observed in mouse cSCCs." (PMID 39075581, 2024). "Our findings demonstrate that ITGAV expression identifies these epithelial plastic cancer cells, which cannot be discriminated from epithelial non-plastic cancer cells by current clinical criteria." (PMID 39075581, 2024). "In addition, both CCK-8 and colony formation assays demonstrated that ITGAV downregulation significantly inhibited the proliferation of both UM1 and UMSCC-5 cancer cells." (PMID 38534932, 2024). "Among these, integrin beta-5 (ITGB5) and its partner integrin alpha-V (ITGAV) were recognized, as they mediate cell–matrix adhesion and play a procancer role in YAPon cancers, while exhibiting an opposing effect by suppressing cell growth in YAPoff cancers." (PMID 38067201, 2023). "The positive weights for CA125 and HE4 indicate a higher predicted likelihood of cancer for those with a higher expression, while the negative weights for ITGAV and SEZ6L indicate a lower predicted likelihood of cancer for those with a higher expression." (PMID 35804849, 2022). "In pan-cancer analyses, ITGAV expression in 26 cancers (with not less than three samples for each cancer) was explored, involving 21,989 samples (n of cancer = 11,537; n of non-cancer = 10,452)." (PMID 35927660, 2022). "ITGAV expression was also identified as a risk factor for disease-free survival of PAAD (p < 0.05), although this was not seen in other cancers." (PMID 35927660, 2022). "At not less than ten cancers, negative relationships can be observed (Pearson correlation coefficient < − 0.2, p < 0.05) of ITGAV expression with memory B cells, CD8 T cells, follicular helper T cells, regulatory T cells, and activated NK cells." (PMID 35927660, 2022). "Therefore, we differentiated PDEs from TEVs using the candidate cancer surface markers ITGA2, ITGAV, and GPC1." (PMID 34948417, 2021).
cancer (continued). "The best performing model for discrimination between benign tumors and borderline tumors + cancer was a 6-biomarker combination (HE4, CA125, ITGAV, CXCL1, CEACAM1, IL-10RB) and age (AUC 0.868, sensitivity 0.86 and specificity 0.82, p = 0.016 for comparison with the reference model)." (PMID 33075095, 2020). "All the mutations in ITGAV were variations of unknown significance (VUS), a genetic change whose impact on cancer risk is not yet understood." (PMID 37174052, 2023). "Enhanced expression of ITGAV (αv subunit), ITGA1 (α1 subunit) and ITGA2 (α2 subunit) in OVCAR5 CBPR cells is indicative of ECM changes consistent with enhanced production of fibronectin and collagen observed in several malignancies and in most EMT-induced cancer models." (PMID 36463238, 2022). "ITGAV in general plays an important role in the regulation of cancer growth, metastasis and tissue remodeling, but upregulation of ITGAV not just increases cellular adhesion but plays an inhibitory role in lipid transport that is essential for surfactant production." (PMID 31492143, 2019). "In addition, CCNE2, PIK3CB, ITGAV, RB1, and BIRC2 involved in cancer pathway were also affected." (PMID 28567416, 2017). "Moreover, ITGAV knockdown in EpCAM+ plastic cancer cells significantly reduced EMT induction in response to TGFβ and blocked the generation of mesenchymal EpCAMneg cancer cells, although cancer cells showed pSMAD3 induction upon TGFβ1 treatment and translocation of pSMAD2 to the nucleus." (PMID 39075581, 2024). "Combined depletion of ITGAV in PDA cells and E- and P-selectins in host mice massively suppresses intraperitoneal carcinomatosis of PDA cells xenografted into immunodeficient mice, confirming the hypothesis of a partly redundant adhesion cascade of metastasizing cancer cells." (PMID 34174926, 2021). "We, as far, do not know whether the decreased level of ITGAV in the urine samples of the PCa patients is related to downregulation of integrin expression in membranes of cancer cells, or it is related to neoplastic rearrangements of prostate gland leading to disruption of prostatic ducts." (PMID 33791193, 2020). "This revealed that ITGAV expression was an independent factor (not affected by TNM stage and clinical stage) for most cancers." (PMID 35927660, 2022).
infection (12 papers, 2016 to 2025). The state of being infected such as from the introduction of a foreign agent such as serum, vaccine, antigenic substance or organism. "Automated cell counting and mitochondrial activity as a marker of cell proliferation showed a strong decrease in cell proliferation in ITGAV-KD cells at day five post infection." (PMID 27363302, 2016). "Notably, VZV OKA strain infection and cell to spread were reduced in ITGAV knockout cells, thus suggesting a potential counter mechanism for T cells to limit varicellovirus entry." (PMID 38887303, 2024). "Although depletion of ITGAV decreased cell proliferation and slightly increased cell death at early time points after infection of proliferating cells, ITGAV-KD cells subjected to adipogenesis effectively underwent differentiation without any signs of cell death." (PMID 27363302, 2016). "Interestingly, infection with H. pylori induced the expression of both KDM4B and ITGAV, thereby augmenting the propagation of CagA signaling, phosphorylation of c-Jun, and activation of IL-8 expression via the KDM4B-c-Jun complex upon H. pylori infection." (PMID 30683841, 2019).
adenocarcinoma (2 papers, 2013 to 2022). A common cancer characterized by the presence of malignant glandular cells. "In addition, ITGAV was significantly over-expressed in tumors showing perineural invasion (P < 0.05), and ITGA5 and ITGA6 were significantly over-expressed in mucinous-type tumors compared with adenocarcinoma (P < 0.05)." (PMID 23705994, 2013).
benign tumors (2 papers, 2020 to 2022). "A 6-biomarker model (HE4, CA125, CXCL1, ITGAV, CEACAM1, IL-10RB and age) was found to be the best model for discrimination between benign tumors and EOC including borderline tumors." (PMID 33075095, 2020).
CNS tumors (1 paper, 2019). "Interestingly, in our study, miR‐367 silencing was able to inhibit stem‐like traits in embryonal CNS tumor cells despite its effects on ITGAV expression, revealing a robust role of this pluripotency‐related miRNA on embryonal CNS tumor aggressiveness." (PMID 31402560, 2019). "A potential relevance of ITGAV in these CNS tumors is unknown and deserves further investigation." (PMID 31402560, 2019).
digestive system cancer (1 paper, 2025). A primary or metastatic malignant neoplasm involving any part of the digestive system. "Bioinformatics methods were employed to investigate the potential oncogenicity of ITGAV, focusing specifically on the analysis of its prognosis, diagnostic value, and immune infiltration level of ITGAV in digestive system cancers." (PMID 40018050, 2025). "Meanwhile, the diagnostic and prognostic value of ITGAV in digestive system cancers was evaluated, and the ITGAV genomic variants were analyzed." (PMID 40018050, 2025). "Notably, ITGAV was positively associated with most immunostimulators and immunoinhibitors in five digestive system cancers: LIHC, COAD, STAD, ESCA, and PAAD." (PMID 40018050, 2025). "In summary, ITGAV demonstrated significantly elevated expression levels in digestive system cancers, which were closely associated with poor survival outcomes and exhibited good diagnostic value, indicating a significant connection between ITGAV and the malignant progression of the tumors." (PMID 40018050, 2025). "Our findings showed that ITGAV upregulation was positively correlated to the poor prognosis and has high diagnostic accuracy (AUC > 0.7), suggesting that it could be a promising potential prognostic and diagnosis biomarker for digestive system cancers." (PMID 40018050, 2025). "For this reason, our study started with a focus on the relationship between ITGAV gene expression and OS, DSS, PFI, and diagnostic accuracy in digestive system cancers." (PMID 40018050, 2025). "The findings indicated that ITGAV expression can accurately predict the prognosis of patients with four digestive system cancers: STAD, PAAD, ESCA, and LIHC." (PMID 40018050, 2025). "The findings of our study showed that the expression of ITGAV exhibited a significant positive relationship with the infiltration of CAFs in digestive system cancers." (PMID 40018050, 2025). "It is worth noting that, among these types of tumors, we found that ITGAV expression was significantly higher in multiple digestive system cancer tissues than in normal tissues, including COAD, ESCA, LIHC, PAAD, and STAD (P < 0.001)." (PMID 40018050, 2025). "In conclusion, our study elucidated the role of ITGAV in digestive system cancers from various aspects." (PMID 40018050, 2025). "Here, we comprehensively investigated the different expression levels of ITGAV in digestive system cancer samples and normal samples by databases." (PMID 40018050, 2025). "Based on our previous findings, we identified that the expression level of ITGAV influences OS in numerous digestive system cancers." (PMID 40018050, 2025). "After comparing the co-expressed genes in these five digestive system cancers, five genes, PKD2, CDH11, OSMR, ITGB1, and BNC2, were further identified as being associated and interacting with ITGAV through the Venn diagram." (PMID 40018050, 2025). "Subsequently, the function of ITGAV in digestive system cancers was described based on bioinformatics analysis, and these findings were validated through in vitro experiments." (PMID 40018050, 2025). "The results indicated that ITGAV was positively correlated with the infiltration levels of most immune cells, and in particular, a significant positive correlation with macrophage infiltration was found in all five digestive system cancers." (PMID 40018050, 2025). "In general, ITGAV displayed a close linkage with immune regulation to provide valuable theoretical proof that can be used as a new immune-related therapeutic target in digestive system cancers." (PMID 40018050, 2025). "We found that ITGAV was highly expressed in multiple digestive system cancers." (PMID 40018050, 2025). "Although these findings suggested the potential of ITGAV as a therapeutic target and prognostic marker, its potential function, prognostic value, and immune characteristics in digestive system cancers remain unclear." (PMID 40018050, 2025).
digestive system cancer (continued). "However, few previous studies focused on the role of ITGAV in digestive system cancers, and to fill this gap, we conducted a large number of data analyses in digestive system cancers." (PMID 40018050, 2025). "However, systematic studies and analyses of ITGAV expression in the broad category of digestive system cancers were still inadequate." (PMID 40018050, 2025). "Furthermore, the expression of ITGAV was closely associated with various immune checkpoints, TMB, MSI, and HRD, as well as some immune and molecular subtypes in different types of digestive system cancers." (PMID 40018050, 2025). "However, more experiments are still needed to reveal the mechanism of action of ITGAV in digestive system cancers." (PMID 40018050, 2025). "Therefore, it is crucial to explore the function of ITGAV in multiple digestive system cancers." (PMID 40018050, 2025). "On the other hand, ITGAV showed a significant negative correlation with the infiltration level of Th17 cells among these five digestive system cancers." (PMID 40018050, 2025).
neurodegenerative disease (1 paper, 2024). A disorder of the central nervous system characterized by gradual and progressive loss of neural tissue and neurologic function. "Further potential relevance to hearing loss mechanisms is that the absence of the ITGAV and ITGAB8 genes has also been shown to cause neurological complications, including disruption of neurovascular development and neurodegenerative disease in murine models." (PMID 38440980, 2024).
respiratory disease (1 paper, 2024). "Some of the identified candidate genes, such as G Protein-Coupled Receptor Kinase 7 (GRK7), ADAM metallopeptidase domain 9 (ADAM9), furin, paired basic amino acid cleaving enzyme (FURIN), and Integrin Subunit Alpha V (ITGAV) were previously associated with bovine respiratory disease susceptibility." (PMID 38892353, 2024).
vascular disorder (1 paper, 2020). A general term used to describe any disease affecting blood vessels]. "Five proteins, THBS2, LASP1, LAMB3, ITGAV, and COL11A1A, were selected according to their GO classification, the Kyoto Encyclopedia of Genes and Genomes (KEGG) pathways in which they can be involved and their relationship with AAA or vascular disorders." (PMID 32605321, 2020).
ITGAV also shares sentences with these, for which no sentence is quoted: myocardial infarction (5 papers); lung squamous cell carcinoma (4); non-small cell lung carcinoma (4); cardiomyopathy (3); chronic lymphocytic leukemia (3); craniosynostosis (3); acute myocardial infarction (2); atherosclerosis (2); coronary artery disease (2); head and neck cancer (2); Hypertension (2); keloid (2); myeloma (2); allergies (1); Alzheimer disease (1); anemia (1); arrhythmogenic right ventricular cardiomyopathy (1); arthrogryposis (1); Atrophy (1); attention deficit-hyperactivity disorder (1); bladder tumors (1); brain abnormalities (1); breast tumor (1); Burkitt lymphoma (1); carcinoma in situ (1); cardiovascular diseases (1); chronic hepatitis B virus infection (1); chronic kidney disease (1); Cirrhosis (1); colon adenocarcinoma (1).
A further 46 diseases each share a sentence with ITGAV in 1 paper.